RN7SL461P (RNA, 7SL, cytoplasmic 461, pseudogene)
Gene: Miscellaneous RNA gene on chromosome 14 (56,824,375 to 56,824,656, reverse strand). Ensembl gene ENSG00000243801.
Homologues: Orthologues: chimpanzee Metazoa_SRP (99% identical), macaque Metazoa_SRP (94% identical). Paralogues in human: RN7SL786P (82% identical), RN7SL2 (81% identical), RN7SL1 (80% identical), RN7SL126P (80% identical), RN7SL3 (79% identical), RN7SL709P (79% identical), RN7SL278P (79% identical), RN7SL679P (79% identical), RN7SL769P (79% identical), Metazoa_SRP (78% identical), RN7SL164P (78% identical), RN7SL45P (78% identical), and 703 more.